VHL (von Hippel-Lindau tumor suppressor)
Diseases named in the same sentence as VHL in open-access papers (continued):
Sharing a sentence is not in itself a finding about the gene and the disease.
tumor (continued). "CCT is involved in both the folding of the VHL tumor-suppressor protein and the assembly of the VHL-elongin BC complex where VHL needs to be coupled to elongin BC to be able to fold correctly." (PMID 30506376, 2019). "Another cell line is RCC4, a VHL mutant derived from a primary tumor widely used as a model for VHL-dependent mechanisms, with a commercially available counterpart cell line with restored wild-type gene." (PMID 30815591, 2019). "Hypoxia-inducible factor 1-alpha (HIF1a) and its regulator von Hippel–Lindau protein (VHL) play an important role in tumour ischemia." (PMID 31323773, 2019). "The rate of new tumor development for all VHL manifestations was highest at age 30–34 years with 0.4 new lesions per year." (PMID 31087189, 2019). "Tumours with monosomy 3 (M3) (n = 34) had a higher expression of HIF1a (p = 0.001) and a lower expression of VHL (p < 0.001) compared to tumours with disomy 3 (D3) (n = 20)." (PMID 31323773, 2019). "To confirm this point we have analyzed the expression of c-MYB in all tumor samples from our cohort and correlated to VHL and MYBBP1A expression." (PMID 30781655, 2019). "The von Hippel-Lindau (VHL) tumor suppressor is one of the few genes harboring a familiar cancer syndrome, i.e. VHL mutations are known to cause a predictable series of events leading cancer in the kidneys and a few selected other tissues." (PMID 30943211, 2019). "The VHL protein (pVHL) can inhibit angiogenesis and tumor growth and affect the stability of hypoxic induction factors (HIFs)." (PMID 31462894, 2019). "RCC is a tumor-type sensitive to VEGFR TKI therapy, likely a result of the Von Hippel-Lindau (VHL) gene loss that commonly characterizes these tumors." (PMID 30796200, 2019). "Five of these patients had a tumor volume less than 20 mm3, and in one PCC patient diagnosed in 2002 with VHL gene mutation, recurrence was observed in 2003, 2005 and 2014." (PMID 31027285, 2019). "The VHL gene is located on chromosome 3p25–26 and codes for VHL protein (pVHL), which is one of the most important tumor suppressor proteins." (PMID 31068970, 2019). "Since the Von Hippel-Lindau (VHL) disease tumor suppressor gene VHL is commonly inactivated in ccRCC, the tyrosine kinase inhibitors (TKIs) that modulate the pVHL-HIF-VEGF signaling pathway have showed treating benefit in patients with advanced ccRCC." (PMID 31311512, 2019). "We demonstrated that expression of HIF1a and VHL as indicators of ischemia are clearly related to tumour genetics and inflammation in UM, and less to tumour size." (PMID 31323773, 2019). "Here, we showed that the expression levels of VHL and microtubule-associated protein 1 light chain 3B (MAP1LC3B, LC3B) were inversely correlated with various tumor grades of RCC tissues." (PMID 30902965, 2019). "We demonstrated that both HIF1a and VHL are strongly related to tumour genetics, and wondered how this related to tumour size." (PMID 31323773, 2019). "Recent published reports indicated that ccRCC tumor cells expressing mutant VHL and the stable expression of HIFs participate in lipid deposition." (PMID 30380599, 2018). "Von Hippel-Lindau (VHL) is an important tumor suppressor that is lost in the majority of clear cell carcinoma of renal cancer (ccRCC)." (PMID 29562667, 2018). "The “tumorlet” cells are reminiscent of the pre-tumor hemangioblast cell clusters observed during RCH development in VHL patients." (PMID 30234140, 2018).
tumor (continued). "VHL protein acts as a tumor suppressor by targeting hypoxia-inducible factors (HIFs) for degradation through an oxygen-dependent mechanism." (PMID 30105105, 2018). "Although the degradation of HIFα is important for the tumor suppressor function of VHL, growing evidence suggests that additional VHL substrates exist." (PMID 29562667, 2018). "A significant lower number of Tregs was detected in the tumor microenvironment of 13 VHL-MUT-RCC as compared to 13 VHL-WT-RCC tumors (1.84 ± 0.36% vs 3.79 ± 0.74% respectively, p = 0.04)." (PMID 30514329, 2018). "Although a role for VHL in DNA repair has not been studied as intensely as its role in angiogenesis and promotion of tumor growth, there have been several studies that support a connection between VHL and DNA repair." (PMID 29435132, 2018). "We measured ascorbate, HIF-1α, and HIF-2α protein and HIF downstream targets BNIP3, CA9, cyclin D1, GLUT1, and VEGF (combined to generate the HIF pathway score) in VHL-defective ccRCC (n = 73) and VHL-proficient pRCC human tumor tissue (n = 41)." (PMID 30555801, 2018). "Biochemically, the protein product of the VHL tumor suppressor gene pVHL acts as the substrate recognition module of an E3 ubiquitin ligase complex." (PMID 30355451, 2018). "The Von Hippel–Lindau (VHL) tumour suppressor gene undergoes bi-allelic knockout in the vast majority of clear cell RCCs." (PMID 30099580, 2018). "This suggests that FN protein changes in the tumour cells and the surrounding matrix play a role in all patients of RCC especially with VHL mutations." (PMID 30009029, 2018). "Von Hippel-Lindau (VHL) disease is an autosomal dominant inherited cancer syndrome, and VHL is identified as a tumor suppressor gene." (PMID 30477447, 2018). "The waiting time from biallelic VHL inactivation to cancer diagnosis ranged from 15 to 30 years, the wide range presumably reflecting differences in rate of tumor growth, acquisition of subclonal drivers, screening practices, and development of symptoms." (PMID 29656891, 2018). "Further, to elucidate the mode of action of TGF-β and it’s abilities to induce tumor aggressiveness depending on the levels of pVHL expression, we utilized two ccRCC cell lines A498 (VHL-/-) and ACHN (VHL+/+) for in-vitro studies." (PMID 29662646, 2018). "One hundred and sixty-one CRC (CCC and CRC-UMF) isolated from the blood of these 25 patients showed mutations of the VHL gene identical to and 21 CRC-UMF displayed mutations of the VHL gene different from those detected in the corresponding tumor tissue." (PMID 29732003, 2018). "The Von Hippel–Lindau (VHL) tumour suppressor gene, located at 3p25, undergoes bi-allelic knockout in the majority of ccRCCs." (PMID 30099580, 2018). "In 90% of cases, these tumours exhibit alterations in the von Hippel–Lindau tumour suppressor (VHL) gene on chromosome 3." (PMID 30123932, 2018). "As with VHL, PBRM1 and SETD2, biallelic inactivation of BAP1 via mutation and loss of heterozygosity fit a two-hit tumor suppressor profile." (PMID 30355451, 2018). "The best-characterized tumor suppressor function of the VHL protein (pVHL) is as the substrate-recognition subunit of an E3 ubiquitin ligase that targets hypoxia-inducible factor (HIF) α-subunits for degradation under normoxic conditions." (PMID 29435132, 2018). "The presence of VHL alteration significantly correlated with a standard prognostic factor, pT3 tumor stage (p = 0.009)." (PMID 30149673, 2018). "Our study in 114 RCC tumors demonstrates an association between the HIF pathway and ascorbate in tumors that is dependent on the presence of a functional VHL tumor suppressor." (PMID 30555801, 2018). "VHL targets hypoxia-inducible factor (HIF) for degradation under normal physiological conditions, whereas in the tumour cell microenvironment, mutation of VHL enables HIF to accumulate in the tumour cells." (PMID 29472550, 2018).
tumor (continued). "It remains possible that some of these tumor samples were VHL-proficient, but given that about 90% of all ccRCC cases contain a dysfunctional VHL protein these samples are very unlikely to influence our dataset." (PMID 30555801, 2018). "VHL is identified as a tumor suppressor gene, which has three exons encoding the VHL protein (pVHL)." (PMID 30477447, 2018). "Nevertheless, prior studies regarding the influence of VHL status on tumor progression and overall outcomes has been conflicting." (PMID 29963258, 2018). "VHL is a tumor suppressor gene that plays a pivotal role in the development of ccRCC.VHL can be altered and transmitted in an autosomal dominant fashion (VHL disease) or in a sporadic manner." (PMID 29568504, 2018). "The authors reported a 75% concordance of the VHL gene alterations detected in peripheral blood with those obtained on matched tumor samples." (PMID 30177639, 2018). "For instance, KDM5C is induced by HIF, and its demethylase activity against global H4K4me3 mark is dependent on HIF in VHL-/-ccRCC cells, and yet it clearly plays an anti-tumor role in ccRCC." (PMID 30355451, 2018). "NKs derived from VHL-MUT patients (#24, #25, #26) displayed higher CD107a exposure versus RCC autologous tumor cells or A498-VHL-MUT cells as compared to SN12C-VHL-WT cells (average CD107a+NK: 4.7 and 2.7% vs 0.3% respectively at 10E:1 T ratio)." (PMID 30514329, 2018). "These distinct roles have been mostly defined in VHL-deficient RCC cells in which HIF-2 has been shown to be necessary and sufficient to maintain tumor growth." (PMID 29481555, 2018). "Hydroxylated HIF-α is recognized by the von Hippel Lindau (VHL) tumor suppressor and targeted for degradation." (PMID 30555801, 2018). "If so, the clonal VHL and TERT driver mutations also seen in this tumor must have preceded the chromothripsis." (PMID 29656891, 2018). "The remaining seven CCC and sixteen CRC-UMF without VHL mutation were all found to derive from the four patients harbouring a wild type VHL sequence in their tumor tissue." (PMID 29732003, 2018). "Preclinical and clinical evidence shows that HIF-2α inhibitors reduce neoangiogenesis and growth of human renal clear cell carcinomas, a neoplasia characterized by VHL tumor-suppressor inactivation." (PMID 29422508, 2018). "The mutation accumulation in trunk genes, especially VHL and MUC4, can regulate cell adhesion, helping tumor cells to escape from the immune system." (PMID 29463849, 2018). "Concerning our observation, VHL was predominantly found to be lost in Fuhrman grade G1 but retained in several Fuhrman G3 tumours." (PMID 28486536, 2017). "The VHL gene, which is responsible for VHL disease, was identified at loci on chromosome 3p as a tumor suppressor gene in clear cell renal cell carcinoma (RCC)." (PMID 28549422, 2017). "The protein VHL is a tumor suppressor that forms E3 ubiquitin ligase complex, which negatively regulates HIF-1α by promoting its polyubiquitination." (PMID 29068413, 2017). "Our high resolution copy number analysis outlined that CNA genes positioned nearest to VHL (16/48 tumour cases) were differentially lost 60kb downstream in 29 ccRCC tumour cases (FANCD 2), but 30kb upstream only in 17 ccRCC tumour cases (IRAK2)." (PMID 28486536, 2017). "We identified 6 samples exhibiting decreased copy number of exon 1 of VHL (hereafter VHLdel-PGLs) in tumor genomic DNA." (PMID 28036268, 2017). "Despite the role of VHL in the hypoxia pathway of the RCC pathogenesis it can be expected that also other genetic alterations are necessary for tumor formation." (PMID 27906674, 2017). "PHDs use molecular oxygen to hydroxylate specific prolyl residues within HIF-α, which creates a binding site for the von Hippel-Lindau (VHL) tumor-suppressor protein." (PMID 29163780, 2017). "Von Hippel-Lindau (VHL) is a tumor suppressor gene involved in oxygen and energy-dependent promotion of protein ubiquitination and proteosomal degradation." (PMID 28969028, 2017).
tumor (continued). "Our findings indicate that shorter telomere length is a new biomarker for tumor risks in VHL patients, which is useful for genetic counseling and prompts future research about the role of telomere shortening in the pathogenesis of VHL‐associated tumors." (PMID 28776935, 2017). "Note, losses in the VHL locus 3p25.3 plus gains in loci at 5q are shared at 5q31.2 and 5q31.1 by at most 21/48 tumours (14/26 G1 vs. 7/20 G3, respectively 13/26 G1 vs. 9/20 G3)." (PMID 28486536, 2017). "Poor outcomes are exacerbated by the presence of a defective VHL tumour suppressor gene which is frequently found in RCC tumours." (PMID 28582447, 2017). "The von Hippel-Lindau (VHL) gene is a tumor suppressor gene and VHL gene alteration occurs in 50-70% of clear cell RCC." (PMID 28103578, 2017). "Our data from off-label use of Octreotide-LAR in a 64-year-old female patient with a severe VHL phenotype showed that 9 months of octreotide treatment led to resultant clinical stability and decreased tumor volume." (PMID 28094316, 2017). "Worth noting, the VHL gene at chromosomal locus 3p25.3 gene displayed only 16 gene losses found in 48 HRO tumours." (PMID 28486536, 2017). "Further studies are needed to clarify the role of imprinted genes located on 11p15 in tumor development of SDHx and VHL mutant PGL/PCC." (PMID 28099933, 2017). "VHL-defective tumor cells have been shown to express high levels of HIF-α subunits (HIF-1α and HIF-2α), leading to the constitutive activation of hypoxia signaling." (PMID 29215599, 2017). "The VHL tumor-suppressor protein is part of an E3 ubiquitin ligase complex that promotes rapid HIF-degradation." (PMID 29163780, 2017). "Alterations in the VHL tumor suppressor stabilizing the hypoxia-inducible factors (HIFs) are the most prevalent molecular features of clear cell tumors." (PMID 29176561, 2017). "There is an obvious phenotypic heterogeneity in the tumor types and onset age between and within VHL families." (PMID 28776935, 2017). "The VHL gene showed losses in only 16/48 tumour genomes of which 14 represent grade G1, but only just 1 loss was detected in Fuhrman grades G2 and G3." (PMID 28486536, 2017). "Targeting VHL-derived tumours with drugs with reduced side effects is urgent to avoid repeated CNS surgeries." (PMID 28662711, 2017). "Previous work has described a role for hif-1 in the long lifespan of animals carrying a mutation in vhl-1, the C. elegans homolog of the mammalian von Hippel-Lindau VHL tumor suppressor gene." (PMID 28758895, 2017). "Our mouse models of pRCC and ccRCC faithfully recapitulate the genomics of human RCC although the incidence of ccRCC tumours that have coincident VHL and CDKN2A inactivation, along with MYC activation is only ∼6%." (PMID 28593993, 2017). "The chromosomal alteration of the VHL tumor suppressor gene leads to the functional inactivation (due to the loss of both alleles) of the von Hippel-Lindau protein (pVHL), an essential component of the cellular oxygen-sensing pathway." (PMID 28891933, 2017). "This group is characterized by downregulation of VHL (n=18), as well as high tumor stage (T3/4, n=13) and grade (G3/4, n=20) suggesting rather advanced disease." (PMID 28212566, 2017). "ccRCC patients with VHL gene mutations revealed an association between strong CXCR4 expression and poor tumor-specific survival." (PMID 28846693, 2017). "In our study, HCaRG overexpression significantly reduced tumor vascularization most probably by suppressing VEGF through the inactivation of AKT/mTOR/HIF signaling independently of abnormal VHL expression." (PMID 29050225, 2017). "The first cluster contains pseudohypoxia-driven tumours including VHL, SDH, EGLN1 and HIF2A mutant tumours." (PMID 29166454, 2017). "In this study, we maintained the VHL-defective ccRCC cell line under long-term hypoxic conditions to partially mimic a stressful environment where tumor cells develop in the human body." (PMID 29215599, 2017).
tumor (continued). "Von Hippel–Lindau (VHL) plays both tumor suppressor and oncogenic roles, and the reason behind is poorly understood." (PMID 28580172, 2017). "Our model is able to reject local fragility for 13 of the 15 peaks containing known tumour suppressors, VHL/FANCD2 and CDKN2C being the exceptions." (PMID 29089486, 2017). "Reintroduction of CPT1A into VHL-defective cells not only reverses the lipid deposition phenotype, but importantly reduces tumor growth in vivo." (PMID 29176561, 2017). "This analysis revealed that VHL-single hit cells exhibit a distinct gene expression profile, different from ccRCC tumor and WT cells." (PMID 27682873, 2017). "In conclusion, VHL-induced miR-204 overexpression leads to suppression of tumor growth by targeting LC3B and therefore inhibiting macroautophagy." (PMID 29165391, 2017). "According to our data, losses of EMC3 (33/48 ccRCC genomes) at 3p25.3 preceded in number losses of VHL 16/48 ccRCC tumour at that locus." (PMID 28486536, 2017). "FHIT synergizes with VHL, another tumor suppressor, to protect against chemically induced lung cancer." (PMID 28811522, 2017). "While SDHB (1p36) and VHL (3p25) are associated with autosomal dominant disease, SDHD (11q23) and SDHAF2 (11q13) show a remarkable parent-of-origin effect whereby tumor formation is almost completely dependent on paternal transmission of the mutant allele." (PMID 28099933, 2017). "Remarkable phenotypic heterogeneity exits in organ involvement and tumor onset age between and within VHL families." (PMID 28776935, 2017). "VHL gene, whose product inhibits induction of tumor cell proliferation by Jade-1 or HIF-1, is the most studied gene in RCC." (PMID 28969028, 2017). "These premises encouraged us to carry out an in-depth analysis of the role of HIF-1α, SDH, and VHL on miR-210 expression by using knockout murine models and analyses of human tumor material." (PMID 28036268, 2017). "Under hypoxic conditions, increased expression of EGLN3 is necessary for survival and G1 to S transition of tumor cells, suggesting that in VHL-single hit cells a condition of modified steady state and feedback regulation exists that favors RCC development." (PMID 27682873, 2017). "Of TCGA KIRC tumours (n=525), 87, 13 and 31% had VHL inactivation, MYC activation and CDKN2A deletion, respectively." (PMID 28593993, 2017). "Von Hippel-Landau (VHL) protein is a potent tumor suppressor regulating numerous pathways that drive cancer, but mutations in VHL are restricted to limited subsets of malignancies." (PMID 29053101, 2017). "Twist1 was mainly expressed in the nuclei and cytoplasm while VHL was located in cytoplasm in tumor tissue." (PMID 28710479, 2017). "Although VHL is a known tumor suppressor, our findings suggest that VHL can have an oncogenic or tumor suppressor role depending on the expression of isoforms and their oligomeric state." (PMID 28580172, 2017). "In over 70% of sporadic ccRCC cases, von Hippel–Lindau (VHL) tumor suppressor gene inactivation through sequence alteration, promoter CpG hypermethylation or loss of heterozygosity has been reported." (PMID 28212566, 2017). "In a previous study wherein the tumor-suppressive effect of B-Myb in VHL disease was investigated, we preliminarily found that knockdown of HIF-2α decreased protein levels of B-Myb in pVHL-deficient 786-O cells." (PMID 28394947, 2017). "We find VHL-deficient cells stably transfected with shVector continue to grow during etoposide delivery, whereas the shNOX4 RCC cells showed reduced tumor volume compared to the start of etoposide injection." (PMID 29051480, 2017). "A major underlying genetic alteration in ccRCC is the von Hippel–Lindau (VHL) tumor-suppressor gene, whose deregulation stimulates an oncologic metabolic shift." (PMID 27139883, 2016). "Different CpG sites in the VHL promoter region were hypermethylated in tumor samples from the same patients, indicating independent VHL promoter hypermethylation during tumorigenesis." (PMID 27383411, 2016).